STAT3 (signal transducer and activator of transcription 3)
Diseases named in the same sentence as STAT3 in open-access papers (continued):
Sharing a sentence is not in itself a finding about the gene and the disease.
melanoma (continued). "Mutations in PTPRD stimulate cell migration and growth in melanoma cell lines, enhance cell proliferation, and abrogate the dephosphorylation of Signal transducer and activator of transcription 3 (STAT3) in human astrocytes." (PMID 33436679, 2021). "Recently, ICAMs have been implicated in the enhanced cell migration and adhesion of melanoma cells onto endothelial cells via the STAT-3 pathway following stimulation from arginase-II, leading to increased STAT-3 activation and ICAM expression." (PMID 34439879, 2021). "As a result, it is proposed that phosphorylation of CREB in the nucleus is blocked by S100B-RSK complex, and CREB-dependent transcription of IL6 is inhibited, leading to the loss of IL6/STAT3 signaling in melanoma." (PMID 34411141, 2021). "Phosphorylation of STAT3 mediates immune escape and is associated with poor survival in melanoma patients." (PMID 34806028, 2021). "Dysregulation of the IL-6/gp130/STAT3 pathway is closely associated with the development of a variety of human malignancies, including melanomas." (PMID 34884773, 2021). "STAT-3 activity has been associated with increasing the likelihood of melanoma relapse after treatment." (PMID 35011682, 2021). "Hyperactivation of STAT3 has been associated with poor prognosis in various malignancies, including melanoma." (PMID 34208965, 2021). "Abrogation of the STAT3 signaling cascade in melanoma caused growth inhibition, apoptosis, and impaired tumor growth and metastasis in animal models." (PMID 32536866, 2020). "Investigation on melanoma samples revealed constitutive STAT3 activation is associated with anti-apoptotic factors such as Bcl-xL upon consistent progression." (PMID 32722030, 2020). "Further, we found that the effects mediated by activating TLR4 are weakened by suppressing STAT3 function with a dominant negative STAT3 variant in melanoma." (PMID 32312954, 2020). "pDC infiltration predicts poor prognosis in PCM and is strongly associated with phospho-STAT3 expression by melanoma cells, suggesting a tumor-induced immunosuppression mechanism." (PMID 32054102, 2020). "Tumor subtype state transition has previously been implicated in melanoma through altering Stat3 expression." (PMID 31956362, 2020). "Increase of STAT3 phosphorylation associated with proliferation was also reproduced in the in vitro model of which we treated B16BL6 melanoma cells with CM from mature adipocytes." (PMID 32722030, 2020). "Accordingly, persistent phosphorylation of STAT3 at Tyr705 and elevated STAT3-dependent transactivation of target genes has been documented and implicated in melanoma progression." (PMID 33396645, 2020). "STAT3 is a critical point of convergence downstream of several hyperactive tyrosine kinase receptors that are either mutated or amplified in melanoma, such as KIT, ERBB4, EPH, FGFR, EGFR and PDGRFA, among others." (PMID 33396645, 2020). "For example, these results strongly suggest an implication of STAT3 in the context of the vast majority of NRAS-mutated melanoma patients who carry a codon 61 mutation and will help further validation of potential drug targets for this subgroup of patients." (PMID 31906480, 2020). "The protein expression of the STAT3/5 ratio and the phosphorylated STAT3/5 ratio are decreased in G6PD-deficient melanoma cells." (PMID 31500396, 2019). "Activation of STAT3 (a signal transducer and activator of transcription) and its signaling pathways have been implicated in melanomas that become resistant to vemurafenib." (PMID 30999681, 2019). "Studies in mice with constitutive or NKp46+ cell-specific Stat3-deficiency indeed show that STAT3 suppresses NK cell-mediated tumor surveillance in melanoma and leukemia models." (PMID 31781102, 2019). "VEGF expression in melanoma metastases can be upregulated by loss of suppressor of cytokine signaling-1 and ensuing activation of signal transducer and activator of transcription 3 (STAT3)." (PMID 29179523, 2017).
melanoma (continued). "It has been recently shown that in melanoma cells the inhibition of the ERK pathway can cause the activation of STAT3." (PMID 28445987, 2017). "Activating STAT3 mutations have been shown to block chemokine expression in melanoma cells and cause T-cell exclusion." (PMID 29348866, 2017). "Early studies implicated IL-6 and its major effector STAT3 as pro-tumorigenic agents in many cancers, including breast, lung, colon, prostate, ovarian, and hematological cancers as well as melanoma." (PMID 27107418, 2016). "In the B16F10 melanoma model, the number and size of metastatic lung nodules was greatly reduced in mice with STAT3-deficient NK cells, following intravenous injection of tumor cells." (PMID 27148255, 2016). "BRAFV600 has been shown to not only stabilize the MCL-1 protein, but to induce MCL-1 transcription through activation of STAT3, rendering melanoma cells susceptible to apoptosis via STAT3 suppression." (PMID 27846237, 2016). "Loss of LIFr expression significantly inhibited melanoma cell migration and inhibited STAT3 phosphorylation." (PMID 26329521, 2015). "Taken together, common driver mutations of malignant melanoma via AP-1 and STAT3 activate miR-21 signal transduction." (PMID 26116372, 2015). "Nevertheless, we next established if the STAT3 rs4796793 was associated with IFNα sensitivity of melanoma cell lines." (PMID 25593920, 2014). "This analysis revealed a clear trend toward an increased IFNα sensitivity of melanoma cell lines with a homozygote STAT3 rs4796793 minor allele." (PMID 25593920, 2014). "STAT1 restricts cell growth and mediates the antitumor effects of IFN-α, while STAT3 is associated with melanoma tumor progression and host immunosuppression." (PMID 24516470, 2014). "The constitutive activation of STAT3 is frequently detected in human cancer, including melanoma, and is associated with poor clinicopathological features and prognosis." (PMID 24344100, 2013). "Taken together, our data indicate that SOID-8 inhibits the JAK2/STAT3 signaling pathway in melanoma cells, associated with induction of apoptosis induced by SOID-8." (PMID 23166634, 2012). "In additional experiments, the hypothesis that DHT prevents the compensatory stimulation of the STAT3 signal in cells of melanoma with a BRAF mutation and augments the lethal effect of a BRAF inhibitor alone was further evaluated." (PMID 39944829, 2025). "In the context of melanoma, tumor-associated B cells that activate STAT3 have been shown to enhance tumor progression through the promotion of angiogenesis, implying that STAT3 in B cells could be a potential target for anti-angiogenic therapies." (PMID 41285707, 2025). "In melanoma, STAT3 activation causes SRY box 2 (SOX2) to be upregulated." (PMID 39944829, 2025). "Interestingly, SNAI2 was previously linked to brain metastasis while activated STAT3 was shown to promote melanoma brain metastasis." (PMID 38635031, 2024). "Moreover, TQ’s growth-inhibitory and apoptosis-inducing actions in renal cell carcinoma and melanoma were linked to the suppression of Jak2/STAT3 by downregulating the phosphorylated level of STAT3." (PMID 38397437, 2024). "The hyperactivation of JAKs/STAT3 is closely linked to cancer immune tolerance, with elevated levels of phosphorylated STAT3 observed across various cancers, including breast, lung, liver, GI, prostate, fibrosarcoma, and melanoma." (PMID 38646539, 2024). "Given that EEF2K positively regulates both SPP1 and p‐STAT3 and SPP1 is positively associated with p‐STAT3 in melanoma, we sought to verify whether EEF2K regulates SPP1 in a STAT3‐dependent manner." (PMID 35184394, 2022). "Therefore, as with RICTOR, STAT3 alterations are associated with the malignant behavior phenotype in melanoma." (PMID 34680615, 2021). "In addition to our published data, these results posit NLRP3 as a key driver of STAT3 in melanoma-associated inflammation." (PMID 34531850, 2021).
melanoma (continued). "As RICTOR overexpression led to an increase in the phosphorylation level of STAT3, it suggests that RICTOR implication in melanoma malignant behavior may be partly linked with STAT3." (PMID 34680615, 2021). "Similar in many tumors, melanoma is also linked to the downstream IL‐6/STAT3 axis." (PMID 34531850, 2021). "An overactive STAT3 is associated with poor prognosis in melanoma patients and drives tumor initiation and malignant progression via induction of several cancer hallmarks, such as apoptosis inhibition, tumor angiogenesis, epithelial–mesenchymal transition (EMT), and stemness." (PMID 31569642, 2019). "The underlying mechanism may be that IL-17 promote STAT3 activity via increasing its phosphorylation in melanoma cells and epithelial cells." (PMID 30800130, 2019). "In addition, metastatic lung nodules are greatly reduced in mice with STAT3‐deficient NK cells when challenged with B16‐F10 melanoma cells." (PMID 31609088, 2019). "Furthermore, in melanoma, STAT3 is constitutively activated and the high expression of phosphorylated STAT3 (p-STAT3) is associated with melanoma progression, and is required to enhance the invasive ability of cancer." (PMID 30250008, 2018). "However, in vivo studies are needed to clarify the high rate of melanoma cell proliferation caused by the constitutive activation of STAT3 signaling resulting from XBP1s-driven IL-6 expression." (PMID 28222747, 2017). "To determine whether the increase in phosphorylated STAT3 was caused by extracellular IL-6 secreted by melanoma cells, we applied IL-6 antibodies to neutralize IL-6 in the medium." (PMID 28222747, 2017). "STAT3 in melanoma tumours is associated with poor prognosis." (PMID 26500281, 2015). "We therefore analyzed pSTAT3 levels in order to determine whether SOCS1 protein expression and basal STAT3 phosphorylation were associated in the panel of melanoma cell lines." (PMID 20398276, 2010). "Furthermore, it is unknown if DHT can prevent STAT3/SOX2 reactivation caused by MAPK pathway inhibitors in BRAF mutant melanoma." (PMID 39944829, 2025). "Among the tested therapy variants, the most significant reduction in melanoma growth in vivo was observed after the intratumoral administration of liposomes containing curcumin and STAT3 siRNA and after using liposomes containing curcumin and STAT3 siRNA with iontophoresis." (PMID 38067351, 2023). "Berberine-mediated STAT3 inhibition reduced IL-10 expression in melanoma cells; reprogrammed M2 tumor-associated macrophages to a tumorsuppressive M1 phenotype; increased tumor cell recognition by T cells; and ultimately reduced tumor burden in melanoma-bearing mice." (PMID 36700235, 2022). "Moreover, STAT3 has also been associated to immunosuppression in melanoma." (PMID 33193402, 2020). "Herein, we review the recent advances of STAT3 and STAT5 targeting in melanoma, explore which autoimmune diseases are causatively linked to STAT3 and/or STAT5 signaling, and propose that these patients may particularly benefit from treatment with STAT3/STAT5 inhibitors." (PMID 31569642, 2019). "Hence, STAT3 inhibitors may hold therapeutic promise as multipurpose drugs for the treatment of melanoma in conjunction with associated ADs." (PMID 31569642, 2019). "Our studies show that STAT3 mediates the function of miR-17 in regulating T-cell activities, thus providing novel insight into the mechanisms that may underlie immune evasion in melanoma cells." (PMID 25594054, 2014). "In addition, the expression of G6PD and its activity, cell cycle-related proteins, apoptosis-related proteins, and STAT3/STAT5 in tumor tissues were determined in order to provide full documentation of the regulatory mechanisms involved with in vivo melanoma growth associated with G6PD." (PMID 23693134, 2013). "Together, our findings revealed that GPR161 promotes melanoma malignancy by linking STAT3 activation to TXNIP suppression and metabolic enhancement." (PMID 41834581, 2026).
melanoma (continued). "On the other hand, a previous study has shown that FNDC3B directly interacts with the signal transducer and activator of transcription 3 (STAT3) and inhibits its activity in melanoma cells." (PMID 41574767, 2026). "The inhibition of Src/STAT3 signalling‐mediated angiogenesis contributed significantly to the anti‐melanoma effects of dioscin." (PMID 41546170, 2026). "AT-I has been shown to reduce the protein expression levels of phosphorylated JAK2 and phosphorylated STAT3 in A375 melanoma cells, consequently downregulating the mRNA levels of STAT3 target genes MMP-2 and MMP-9." (PMID 41599296, 2026). "Given that STAT3 is one of the crucial pathways involved in melanoma, agents that suppress melanoma progression can do so by inhibiting STAT3 activity." (PMID 41463281, 2025). "In our previous investigation, we found that inhibiting the MAPK pathway can reactivate signal transduction and transcription activator 3 (STAT3) in BRAF mutant melanoma cells." (PMID 39944829, 2025). "STAT3 establishes a reciprocal relationship between melanoma cells and immune cells in favour of tumour evasion and plays an important role in regulating the psoriasis-inducing IL-23/IL-17 axis." (PMID 40868162, 2025). "Further studies are warranted to determine how nNOS-mediated NO regulates the IFN-γ/STAT3 signaling axis in melanoma cells within the tumor microenvironment." (PMID 39941844, 2025). "In vitro studies have shown that DHT suppresses the development and multiplication of BRAF mutant melanoma cells, prevents the compensatory stimulation of the STAT3 signal in these cells, and improves the therapeutic efficacy of MAPK inhibitors." (PMID 39944829, 2025). "PTX has been shown to suppress both constitutive and IL‐6‐induced STAT3 activation in a dose‐dependent manner, as observed in A375 melanoma cells." (PMID 40387460, 2025). "The excessive IL-6 secreted by DCs stimulates STAT3 signaling in melanoma to upregulate MMP9 expression, thereby promoting tumor cell invasion." (PMID 40908470, 2025). "In melanoma, the tumor microenvironment induces the upregulation of Interleukin 6 Receptor (IL-6R) and Interleukin 10 Receptor (IL-10R) on DCs, activating the STAT3 signaling pathway and suppressing the Toll-like receptor (TLR)-driven maturation program." (PMID 41050070, 2025). "In a RET transgenic melanoma mouse model, researchers identified a relationship between IL-6 levels, phosphorylated STAT3, and CCR5 expression in tumor-infiltrating MDSCs." (PMID 40636453, 2025). "Intriguingly, PAI-1 also drives TAMs M2 polarization through the JAK/STAT3 pathway, thereby sustaining an immunosuppressive environment in melanoma." (PMID 41008624, 2025). "When applied topically by iontophoresis, these dual‐drug‐loaded LbL‐AuNPs significantly suppressed tumor growth and reduced STAT3 expression in melanoma mouse models." (PMID 40166646, 2025). "This protection against ferroptosis in the tumor environment highlights the potential of targeting the IL-9/STAT3/fatty acid oxidation pathway to enhance T cell –based therapies for melanoma." (PMID 40636453, 2025). "In melanoma cell lines, the loss of suppressor of cytokine signaling-1 (SOCS-1) expression is correlated with increased STAT3 signaling and subsequent overexpression of MMP-2, basic fibroblast growth factor (bFGF), and VEGF." (PMID 39780275, 2025). "This combination also blocks the MAPK and STAT3/SOX2 pathways, which effectively slows or stops secondary drug-resistant melanoma cell growth and proliferation as well as causes death." (PMID 39944829, 2025). "For instance, in murine myeloid cells, deficiency of the m6A methyltransferase METTL3 activates STAT3 and NF-κB signaling, promotes the expression of M2-associated genes, and enhances tumor growth and metastasis in B16F10 melanoma." (PMID 41008624, 2025). "Another lncRNA upregulated by STAT3 is ZBED3-AS1, the expression of which is increased in melanoma and is associated with worse survival." (PMID 41463281, 2025).
melanoma (continued). "Previous studies showed that Arg-II can promote melanoma metastasis and adhesion to endothelial cells by activating the STAT3 pathway." (PMID 40177131, 2025). "A chronic inflammatory tumor microenvironment, rich in factors such as IL-6, has been reported to activate STAT3 and concomitantly stimulate the Wnt pathway in melanoma, creating a vicious cycle that promotes CSC self-sufficiency and tumor progression." (PMID 40806546, 2025). "Finding a safe and efficacious combination of STAT3 inhibitor and MAPK inhibitor to treat melanoma with BRAF mutation is therefore a potential therapeutic strategy." (PMID 39944829, 2025). "IL-17 is known to promote melanoma progression by upregulating IL-6 and activating the signal transducer and activator of transcription 3 (STAT3) pathway, contributing to tumor growth and immune modulation." (PMID 40332093, 2025). "The interaction between melanoma cells and microglia supports BM progression through melanoma-derived IL-6, which enhances STAT3 phosphorylation and SOCS3 expression in microglia, thereby aiding melanoma cell survival." (PMID 40076927, 2025). "Earlier studies showed that LILRB4 regulates melanoma, multiple myeloma, and leukemia, via activation of STAT3 and inhibition of NF-κB." (PMID 41102383, 2025). "Silibinin’s impact on STAT3 also indirectly attenuates PD-L1 expression, as shown in melanoma models where STAT3 blockade reduced PD-L1 and restored T-cell function." (PMID 40650040, 2025). "Immature myeloid cells (MDSCs) are attracted by CSCs into the tumor, where they exert their immunosuppressive function and contribute to the maintenance of melanoma stemness by secreting factors such as IL-6 that activate the STAT3 pathway in tumor cells." (PMID 40806546, 2025). "We observed that a subfraction of melanoma exhibits constitutive IκBζ protein expression, which leads to enhanced STAT3 and NF-κB activation, thereby increasing the expression of pro-inflammatory cytokines and chemokines." (PMID 40562773, 2025). "IL-6 can promote the proliferation, survival, and invasiveness of melanoma cells by activating the signal transducer and activator of transcription 3 (STAT3) signaling pathway." (PMID 41346595, 2025). "It is noticeable that IL-17 can promote the growth of melanoma by up-regulation of IL-6 and the signal transducer and activator of transcription 3, demonstrating the possible involvement of Corynebacterium in the appearance of melanoma." (PMID 40431165, 2025). "In melanoma model, napabucasin (STAT3 inhibitor) promotes apoptosis of MDSCs in human peripheral blood and mouse bone marrow, thereby enhancing antitumor immunity and prognosis." (PMID 40612857, 2025). "Melanoma patients with brain metastasis had decreased STAT3 activation and increased PD-L1 levels in sEVs as compared to patients without brain metastasis, possibly because of systemic immunosuppression in melanoma brain metastasis patients." (PMID 40285800, 2025). "Our results demonstrated that CCNB1-high melanoma cells secrete elevated IL-6, a known activator of STAT3 signaling in NK cells." (PMID 40430484, 2025). "STAT3 is constantly activated in melanoma cells, and highly metastatic melanomas are shown to have higher levels of activated STAT3." (PMID 39941844, 2025). "SRC kinase inhibition impedes STAT3 signaling, thereby attenuating the proliferative capacity of melanoma cells." (PMID 40399946, 2025). "In one study, imatinib mesylate and anti‐STAT3 siRNA were encapsulated within layer‐by‐layer assembled gold NPs (LbL‐AuNPs) for melanoma treatment." (PMID 40166646, 2025). "After quercetin therapy, melanoma cells downregulate STAT3-targeted genes MCL-1, MMP-2, MMP-9, and VEGF, which increase cell proliferation, migration, and invasion." (PMID 38398617, 2024). "Both, STAT3 and TNFα signaling have been described to drive the transition of differentiated melanoma cells toward dedifferentiation." (PMID 39398277, 2024).